ITGA1 (integrin subunit alpha 1)
Diseases named in the same sentence as ITGA1 in open-access papers (continued):
Sharing a sentence is not in itself a finding about the gene and the disease.
tumor (continued). "In contrast, the tumor-specific cluster C3 appears less differentiated with features typical of CD56brightCD16neg NK cells (NCAM1, CD2, CD27, SELL, CD69) as well as a signature of tissue residency (CD69 and ITGA1) and of TGF-β-induced genes (SMAD7, TGFB1, PMEP1, SKIL)." (PMID 41145419, 2025). "Besides, we found a positive correlation between the expression of ITGA1 and infiltration of all types of immune cell, but not tumor purity." (PMID 34660316, 2021). "But whether the abundance of ITGA1 in serum and tissue could be used as early diagnosis and treatment of a tumor marker has not yet reported." (PMID 32071551, 2020). "In addition, the average optical density (AOD) values of ITGA1 IHC showed that the overall ITGA1 protein in CRC tumor tissue was more abundant than their matched adjacent non-cancerous tissues (p<0.001)." (PMID 32071551, 2020). "Suggestively, the functional interaction between PLA2R1 and β1 integrin may favour ITGA2 in LNCaP cells due to the lack of ITGA1-expression resulting in a decreased tumour growth and tumour-suppressive role of PLA2R1 in vivo." (PMID 30542512, 2018). "After tumor excision, morphological analysis showed that downregulation of integrin α1 subunit/ITGA1 expression did not affect the morphology of HT29 tumor cells, whereas for the T84 line, the sh-ITGA1 cells were smaller in size than the sh-ctl cells, which had a cylindrical shape." (PMID 28933766, 2017). "Besides, we found that ITGA1 could activate RAS/MEK/ERK signaling pathway cascades and led to activation of Ras and ERK1/2 in CRC cells, which in turn activated c-Myc, subsequently promoted tumor cells proliferation, migration, invasion and tumorigenicity." (PMID 32071551, 2020). "Notably, normal pancreatic ductal epithelial and acinar cells stain negative for ITGA1, while tumor tissue is highly positive across multiple patients, predominantly in the epithelial compartment – high ITGA1 expression is detected in approximately 42% of patient samples." (PMID 28855593, 2017). "The expression of ITGA1 and ITGA9 was correlated with the infiltration of all types immune cell in the SKCM TIME, but not tumor purity." (PMID 34660316, 2021). "Surprisingly, although our in vitro data demonstrate that silencing ITGA1 reduces PDAC cell survival and the frequency of tumor-initiating ALDH1hi PDAC cells, ITGA1 depletion did not affect the in vivo average weight of the primary tumors isolated from the CAM tissue." (PMID 28855593, 2017).
cancer (50 papers, 2011 to 2025). A tumor composed of atypical neoplastic, often pleomorphic cells that invade other tissues. "A mutually exclusive mutation pattern between ITGA3 and ITGA1/2 suggested their different roles in cancer development." (PMID 39436262, 2024). "Another cancer-associated module, the adhesion cluster, shows conceptual similarity to the μ-21-specific corresponding cluster, though only three integrin family proteins (ITGA1, ITGA2, ITGAV) are shared between them." (PMID 41373892, 2025). "The ITGA1 gene encodes the α1 subunit of the integrin receptor, which heterodimerizes with the β1 subunit to form cell surface receptors for collagen and laminin, promoting tumorigenicity in malignant tumors." (PMID 37694778, 2024). "Considering the fact that ITGA1, encoding the α1 integrin, is found pervasively downregulated in the majority of human cancers, it is conceivable that α1 integrin may play a tumor suppressive role." (PMID 34715893, 2021). "Moreover, although genomic alteration is a rare event for ITGA1 at the population level given an average mutation rate of 2.5%, it is the most frequently deleted integrin gene in human cancers." (PMID 34715893, 2021). "The result pinpointed ITGA1 and ITGA2 as the two genes with the highest proportions of deep loss in PCa compared to other cancer types." (PMID 38169150, 2024). "Next, we explored how HDAC inhibition repressed the expression of Itga1 in mesenchymal cancer cells." (PMID 34874914, 2022). "In The Cancer Genome Atlas, ZEB1 mRNA levels are positively correlated with ITGA1 mRNA levels in multiple cancer types." (PMID 34874914, 2022). "ITGA1 is a typical adhesion molecule in cancer cells that mediates cancer cell behaviors, especially when combined with collagen." (PMID 33669233, 2021). "Cancer Pathway cDNA microarray analysis revealed that DACT1α down-regulated cell adhesion receptors from the integrin family including ITGA1, ITGA2, ITGA3 and ITGB3." (PMID 27833078, 2016). "Furthermore, Heatmap analysis showed DNAJC10 overexpression reduced transcription of CAMs related genes such as ITGAV, SEMA3C, DPP4, and ITGA1, which are reported to enhance cancer cell migration and invasion." (PMID 41191192, 2025). "Importantly, RNA-seq indicated DNAJC10 downregulates CAMs-related genes such as ITGAV, SEMA3C, DPP4, and ITGA1, which promote cancer cell migration and invasion." (PMID 41191192, 2025). "Aberrant activation of ITGA1 is inextricably related to the development of various cancers." (PMID 39502752, 2024). "Furthermore, we found that some ITGs such as ITGA3, ITGA6 ITGA11, ITGB4, ITGB6, etc. were frequently upregulated in human cancers, whereas ITGs including ITGA1, ITGA7, ITGA8, ITGA9 and ITGB3, etc. were usually downregulated." (PMID 34222028, 2021). "Integrin α1 (ITGA1) belongs to integrin family and involves in regulating cell adhesion, invasion, proliferation and tumorigenicity, its expression is up-regulated in various cancers, including CRC." (PMID 32071551, 2020). "Together with ours, these data suggest that ITGA1 may be a key molecule to engage the cancer cell progression." (PMID 32071551, 2020). "To gain a better understanding of the potential roles played by individual integrins in different cancer-contexts, we chose ITGA10 and ITGA1 for further analysis in detail." (PMID 34715893, 2021). "Thus, it may be relevant to characterize ITGA1 function further in these other cancer types." (PMID 28855593, 2017). "COMMD7, ITGA1, RAB3D, and TNFAIP2 have all been shown to be upregulated in various cancers including PDAC." (PMID 28922540, 2017). "Platelet activation, focal adhesion, proteoglycans in cancer, axon guidance, phagosome, glutamatergic synapse and MAPK1, FRS2, FDGFRA, SHC1, ITGB2 and ITGA1 may be the core bio-pathway and genes involved in direct intervention, respectively." (PMID 28380454, 2017).
cancer (continued). "Enhanced expression of ITGAV (αv subunit), ITGA1 (α1 subunit) and ITGA2 (α2 subunit) in OVCAR5 CBPR cells is indicative of ECM changes consistent with enhanced production of fibronectin and collagen observed in several malignancies and in most EMT-induced cancer models." (PMID 36463238, 2022).
infection (33 papers, 2015 to 2025). The state of being infected such as from the introduction of a foreign agent such as serum, vaccine, antigenic substance or organism. "C5 was also increased in the infected samples, and these cells co-expressed Eomes and Itga1, and were especially prominent in the infected Tbx21-/- sample, suggesting that this cluster includes the Eomes+ CD49a+ cells that arose in the liver after infection." (PMID 31393266, 2019). "Conversely, we selected the HCC cell lines SMMC-7721, Huh7, and HCC-LY5, which intrinsically express higher levels of ITGA1 to knock down endogenous ITGA1 expression via shRNA and control lentiviral infection." (PMID 28264467, 2017). "ITGA1 displayed reduced H3K27me3 levels and increased expression after infection in resistant birds at 10 dpi (fold-change = 3.16x, FDR = 0.0757)." (PMID 25896894, 2015). "However, vaccinated mice exhibit an undulatory reciprocal increase of Itga1 and Itga2 expression during infections." (PMID 33202767, 2020). "The top upregulated genes in KSHV lytic and mixed infection spots are predicted to encode proteins that regulate angiogenesis including ADAMTS9, KDR and PGF, endothelial cell development including KDR and STC1, and cell-substrate adhesion, SPRY4, ITGA1, ADAMTS9, KDR, MMP12." (PMID 39386738, 2024). "ITGA1, another gene downregulated in trophoblasts from CZS-affected twins after ZIKVBR infection, interacts with the extracellular matrix, particularly with collagen and laminin." (PMID 32745093, 2020). "Genes involved in the control of cell migration were also represented in the HP1 list (e.g. Ccr2, Ccr5, Itga1, Itgb1, Gpr183, Rgs16), with some having an essential role in the recruitment of CD8 T cells in the lung following infection by a pathogen." (PMID 27883012, 2016). "The expression levels of ITGA1, ITGA5, FAK, PIK3R1, PIK3CA and AKT1 were significantly higher in the 1 MOI L. salivarius-treated group, than in untreated cells at 2, 8, and 16 h post-PEDV infection." (PMID 34957282, 2021).
cardiovascular disease (1 paper, 2025). "Comparative transcriptomic analysis revealed that genes related to cardiovascular disease (e.g., Sgcb, Adcy2, Itga1, Itgb8, Ifng, and Gpc1) were upregulated in the livers of R. pruinosus compared to carnivorous and omnivorous rodents, indicating a higher cardiovascular disease risk." (PMID 40941321, 2025).
ITGA1 also shares sentences with these, for which no sentence is quoted: vitiligo (15 papers); influenza infection (13); viral infection (9); prostate carcinoma (6); arterial hypertension (2); bladder cancer (2); fibrosis (2); gastrointestinal tumor (2); head and neck tumors (2); liver cirrhosis (2); lung squamous cell carcinoma (2); metastatic melanoma (2); non-small cell lung carcinoma (2); polyp (2); tuberculosis (2); abortion (1); adenocarcinoma (1); alopecia areata (1); Alzheimer disease (1); ankylosing spondylitis (1); Anxiety (1); arrhythmogenic right ventricular cardiomyopathy (1); atrial fibrillation (1); autoimmune hepatitis (1); bacterial infection (1); basal cell carcinoma (1); bladder tumors (1); bladder urothelial cancer (1); breast invasive carcinoma (1); breast tumors (1).
A further 52 diseases each share a sentence with ITGA1 in 1 paper.